TNF (tumor necrosis factor)
Diseases named in the same sentence as TNF in open-access papers (continued):
Sharing a sentence is not in itself a finding about the gene and the disease.
psoriasis (continued). "Imiquimod-induced psoriasis mice model and TNF-α or IL-17A induced HaCAT cells, an experimental model in vitro for psoriasis, were constructed to explore the effect of BRD4 inhibition on psoriasis and the specific mechanism about MAPK pathway." (PMID 34674702, 2021). "Psoriasis is a chronic inflammatory skin disease characterized by accelerated tumor necrosis factor-α (TNF-α)/interleukin-23 (IL-23)/IL-17 axis and hyperproliferation and aberrant differentiation of epidermal keratinocytes." (PMID 34501328, 2021). "In this study, we focused on patients with psoriasis with both nail and joint disease being treated with tumor necrosis factor-α inhibitors by dermatologists." (PMID 34834435, 2021). "Several signaling pathways including the nuclear factor κB (NF-κB), Mitogen-activated protein kinase (MAPK), mammalian target of rapamycin (mTOR), and tumor necrosis factor α (TNF-α) play crucial roles in the onset of psoriasis." (PMID 34113484, 2021). "Comparing DNA methylation profiles of “all psoriasis” patients before and after treatment with anti-TNF or anti-IL17A directed agents, we identified 1,907 DMPs (1,359 hypo- and 548 hypermethylated) annotated to 1,380 genes." (PMID 34746142, 2021). "Currently, four anti-TNF-α agents are in use for psoriasis: adalimumab, certolizumab pegol, etanercept, and infliximab." (PMID 34938746, 2021). "NF-κB can bind to the promotor of several pro-inflammatory cytokines such as IL-1β, IL-6 and TNF-α that are involved in the pathogenesis of psoriasis." (PMID 33801280, 2021). "Until now, there are biologics in four different classes (anti-TNF-α, anti-IL-17, antiIL-12/IL-23p40, and anti-IL-23p19) have been approved for the treatment of moderate-to-severe psoriasis." (PMID 34938746, 2021). "Biologic therapies involving TNF-α antagonists are widely used for the long-term management of moderate to severe vulgaris psoriasis in clinical practice." (PMID 34395618, 2021). "In fact, paradoxical psoriasis developed during anti-TNFα therapy showed an increased IFN signature in affected skin." (PMID 34680599, 2021). "The TNF-α and IL-17 inhibitors for the treatment of moderate to severe psoriasis included adalimumab, infliximab, etanercept, certolizumab, secukinumab, ixekizumab, and brodalumab." (PMID 34276352, 2021). "Tumor necrosis factor-alpha (TNF-α) inhibitors are frequently used for the management of type 1 helper T-cell (Th1) immune-mediated chronic inflammatory conditions such as psoriasis and Crohn's disease." (PMID 34159000, 2021). "Recent major researches advancements have significantly expanded our understanding of psoriasis pathophysiology, resulting in the development of highly effective targeted therapies, such as anti‐TNFα, IL‐12/23‐inhibitors, IL‐17‐inhibitors, or IL‐23‐inhibitors." (PMID 34436817, 2021). "The inflammatory response in psoriasis is mainly driven by T cells, especially T helper cells (Th17), and is mediated by different cytokines, especially TNF-α, IL-17, IL-23 but also other cytokines such as IFN-γ, IL-2, IL-6, IL-8, IL-17, IL-18 and IL-22." (PMID 34640327, 2021). "In this study, we investigated switching patterns and determinants for switching in patients with RD, IBD, or psoriasis initiating treatment with TNFα inhibitors in the Netherlands between July 2012 and December 2017." (PMID 34302442, 2021). "By addition of the psoriasis cytokines from the in vitro experiments (IL-17A, TNF-α, IL-22, 20 ng/mL each), an inflammatory milieu typical for psoriasis was simulated." (PMID 33801280, 2021). "As expected, drugs targeting TNF-α have been applied in the clinic and have shown promising therapeutic effects on psoriasis." (PMID 34168554, 2021). "Increased miR-146a has a strong positive correlation with IL-17A in psoriasis patients and can be induced by IL-1β, TNF-α, and IL-17A in human proliferating keratinocytes, indicating its potential roles downstream of IL-17A/TNF-α signals." (PMID 33718413, 2021).
psoriasis (continued). "It is well-accepted that cytokine-mediated inflammatory immune responses are involved in the development of psoriasis, including IL-17, IL-23, TNF-α, etc.." (PMID 34881280, 2021). "PPPs also attenuated the expressions of CD3 and Ki67 in psoriasis-like mouse skin and suppressed the serum or skin levels of pro-inflammatory cytokines, such as tumor necrosis factor alpha (TNF-α), interleukin 6 (IL-6), IL-1β, IL-8, IL-17, and IL-23." (PMID 35153762, 2021). "Along TNF, other cytokines such as IL-17 and IL-23 are considered key drivers of chronic inflammation in psoriasis." (PMID 34298932, 2021). "Anti-tumor necrosis factor-α (TNF-α) agents have been used in the treatment of psoriasis for several years." (PMID 34790055, 2021). "Significant progress has been made in the management of psoriasis by the use of targeted biological drugs, initially limited to tumor necrosis factor-α (TNF-α) inhibitors." (PMID 34149708, 2021). "Positive correlations between MMP-3 level and proinflammatory cytokines IL-12p/70, IL-17A, and TNF-α recognized in our study confirm MMPs and Th1 and Th17 cytokines' cross talk in the inflammatory regulation in psoriasis." (PMID 34305455, 2021). "Smoking may affect clinical variability or course of psoriasis because of causes or increases in oxidative stress, functional morphological changes in polymorphonuclear leukocytes, and release of chemotactic factors and cytokines like interleukins, TNF-alpha, and transforming growth factor beta." (PMID 34123557, 2021). "In psoriasis, IL–6 production is increased, which synergizes TNF-α and IL–1 to advance the hyperproliferation of epidermis by its activity on epidermal growth factor receptor." (PMID 34947782, 2021). "After treatment with etanercept (anti-TNF), melanogenesis-related genes were significantly upregulated in the skin lesions of patients with psoriasis." (PMID 34603597, 2021). "The infiltrated neutrophils produce IL-6, IL-17A, and TNF-α to stimulate keratinocytes, resulting in positive feedback to deteriorate psoriasis." (PMID 33754014, 2021). "Patients with psoriasis treated with tumor necrosis factor (TNF) inhibitors or IL-12 and -23 inhibitors report improved mood." (PMID 34828770, 2021). "Our previous studies have demonstrated that the expression levels of IL-23, IL-17, IFN-γ, and TNF-α in the serum of patients with psoriasis were significantly increased." (PMID 33995034, 2021). "Immunologic analysis of anti-TNF-α induced eczema and psoriasis detected elevated IL-17A, IL-23, and IFN-γ serum levels in CD patients with skin lesions." (PMID 33802483, 2021). "A drug used in the treatment of psoriasis of moderate and acute strength is the monoclonal antibody anti-TNF–adalimumab." (PMID 33562571, 2021). "Frequently targeted genes include IL‐23, IL‐17, IL‐36, and TNF‐α, as these genes play a key role in pathogenesis of psoriasis." (PMID 34589595, 2021). "Consistent with the perturbed TNF/IL-12/IL-6 secretion, we found that Zc3h12c−/− mice had ~2-fold lower murine Psoriasis Severity Index (mPASI) score than Zc3h12c+/+ mice at days 3–4, the peak of IMQ-induced psoriatic lesions." (PMID 34215755, 2021). "TNF-α can induce the production of cytokines to amplify inflammation in psoriasis (Boehncke and Schön, 2015)." (PMID 34925011, 2021). "Increased levels of TNF-α, IL-17 and IL-22 are frequently observed in chronic inflammatory skin diseases, including psoriasis, and IL-17 and IL-22 in particular are reported to have a synergistic relationship during inflammatory responses." (PMID 33919521, 2021). "Recently, the association of the TLR5 rs5744174 (A > G) polymorphism with the response to biological drugs indicated in moderate-to-severe psoriasis (anti-TNF: n = 376; UTK: n = 230) has been evaluated in patients from Denmark." (PMID 33921427, 2021).
psoriasis (continued). "The majority of these lesions are identified as psoriasiform (paradoxical psoriasis induced TNF-alpha agent) with different morphologies consisting of pustular psoriasis, guttate; and erythrodermic or inverted psoriasis." (PMID 33936220, 2021). "Subjects with severe psoriasis received systemic therapy in 73% (acitretin 54%, methotrexate 23%, etanercept 18%, and anti-TNF 18%)." (PMID 34064387, 2021). "Of interest, the role of anti- TNF-α treatment in psoriasis and psoriatic arthritis is already well documented." (PMID 34082764, 2021). "The risk of coronavirus disease 2019 (COVID‐19) and its complications among patients with psoriasis treated by tumor necrosis factor inhibitors (TNFis) remains to be decisively delineated." (PMID 34033207, 2021). "The non-targeted metabolomics (LC-MS) was also performed to measure metabolite alterations in severe psoriasis after anti-TNF-α treatment." (PMID 33391503, 2021). "One of the newest studies, one showed that intradermal injection of recombinant IL-33 alone can induce psoriasis-like dermatitis through the transcriptional upregulation of such genes as IL-17, TNF, and other pro-inflammatory chemokines." (PMID 34884710, 2021). "One male patient had concomitant psoriasis and four out of five patients had previously failed anti-TNF-α therapies." (PMID 34572354, 2021). "Th17 lymphocytes differentiate under the influence of IL-23, IL-1β, TGF-β and IL-6, secrete IL-17A, IL-17F, TNF-α, IL-21, IL-22, and IL-26, and they play a crucial role in the maintenance of psoriasis chronic inflammation." (PMID 34769005, 2021). "Although there have been limited studies, recent research proposed a difference in the expressions of TNF-α-IL-17-IL-22 in pediatric psoriasis patients compared to those of adult psoriasis patients." (PMID 34440145, 2021). "On the other hand, biological agents targeting TNF, IL-23 and IL-17 have shown promising efficacy during the clinical treatment of psoriasis, while IL-6 inhibitors, IL-21 inhibitors and recombinant human IL-10 treatment didn’t attain the results as expected." (PMID 34975883, 2021). "Of interest is that TNF-blockers are successfully used in the treatment of inflammatory skin diseases such as psoriasis." (PMID 33805042, 2021). "Of the 12 studies, a total of 692 patients suffered psoriasis induced by TNF-antagonists, and 137 patients stopped or switched to biological agents, and over 50% of them had good prognosis." (PMID 34678884, 2021). "In psoriasis, lipopolysaccharide mediates nuclear transduction of NF-κB, then proinflammatory factors including TNF-α, IL6, and prostaglandin E (PGE) up- regulate in keratinocytes." (PMID 34122426, 2021). "Serum TNF-α and endocan levels in patients with psoriasis were significantly increased, and consistent with previous studies of coronary heart disease, endocan levels were positively correlated with TNF-α and the average carotid intimal media thickness." (PMID 35071362, 2021). "This case is relevant due to the scarcity of reports on late pulmonary adverse effect of anti-TNF treatment of psoriasis." (PMID 34001401, 2021). "A study with 376 patients from Denmark diagnosed with moderate-to-severe psoriasis evaluated the effect of this polymorphism on response to UTK and anti-TNF drugs (PASI 75 at 12 weeks)." (PMID 33921427, 2021). "Macrophages are largely infiltrated in the dermal layer of psoriasis to release cytokines IL-23, IL-6, and TNF-α during the development of the lesion." (PMID 34054833, 2021). "TNF-α levels in HS skin were higher (5-fold) compared to those in psoriasis and they tended to correlate with disease severity." (PMID 34572354, 2021). "We can state that TNF-α is a less “skin-specific” molecule, than the IL-23/IL-17 axis, but that, according to the current evidence, in psoriasis considered as a systemic inflammatory disease remains a “hallmark”." (PMID 34829740, 2021).
psoriasis (continued). "In the confirmed positive group of psoriasis and HS patients n = 5, 4/5 were on anti‐TNF inhibitors, which is unsurprising as 41% of the total cohort were on this type of biologic." (PMID 34235510, 2021). "Systemic inhibitors of TNF such as etanercept (a soluble TNF receptor), infliximab and adalimumab (anti‐TNF antibodies) have been approved for the treatment of psoriasis and RA (Meier, Frerix, Hermann, & Muller‐Ladner, 2013)." (PMID 31999357, 2021). "Clinical studies and targeted therapies have demonstrated that the cytokines TNF, IL-23, and IL-17A have pivotal roles in psoriasis pathogenesis." (PMID 34215755, 2021). "A recent study revealed that the expressions of TNF-α and IL-17 in the skin lesions of pediatric psoriasis patients have been shown to be different from those of adult psoriasis patients." (PMID 34440145, 2021). "The prototypical example is biological agent-induced psoriasis, due to a TNF-α/type-1 IFN cytokine imbalance: TNF-inhibitors (TNFi) block TNF-α, which results in uncontrolled activation of plasmacytoid dendritic cells (pDCs), with surplus production of IFN-α." (PMID 34195265, 2021). "Anti-TNF inhibitors were the first class of biologics approved for psoriasis, in line with the pleiotropic role of TNF in inflammation." (PMID 34362923, 2021). "Many pieces of evidence demonstrated the crucial role of TNF-alpha in psoriasis pathogenesis, like elevated levels of TNF-alpha in both blood and skin lesions at the disease activation time." (PMID 33936220, 2021). "Here we perform in-depth immunomonitoring of blood immune cells of 67 patients with psoriasis, before and during therapy with the anti-TNF drug adalimumab, to identify immune mediators of clinical response and evaluate their predictive value." (PMID 34362923, 2021). "Keratinocytes are the main sources of gene expression that accelerate the progress of psoriasis because the enhanced production of TNF-α and IFN-γ promotes inflammation." (PMID 34641629, 2021). "The objective of the current study was to compare drug survival of ixekizumab to that of TNF inhibitors (TNFi) and non‐ixekizumab IL‐17 inhibitors (IL‐17i) among real‐world patients with PsO in the Corrona Psoriasis Registry." (PMID 33491259, 2021). "Patients with psoriasis receiving anti-TNF immune targeting and fumaric acid ester (FAE) have been shown to have a better prognosis." (PMID 34372872, 2021). "Biologics block specific cytokines (tumor necrosis factor-alpha (TNFα), interleukin (IL)-12, IL-23, or IL-17) in the psoriasis pathogenesis pathway." (PMID 34656148, 2021). "For a long time, psoriasis was assumed to be mediated by Th1 cells through the secretion of TNF-α, IFN-γ, IL-2, and IL-12." (PMID 33967781, 2021). "The increased production of pro-inflammatory mediators and chemokines such as IL-1, IL-6, IL-23, IL-17, and TNF-α plays a crucial role in the pathogenesis of psoriasis." (PMID 35153762, 2021). "Biologics, such as TNF-α inhibitors, IL-12/IL-23 inhibitors, IL-17 inhibitors, and IL-23/IL-39 inhibitors are now considered first-line therapy in moderate to severe psoriasis." (PMID 34884596, 2021). "The elevated level of TNF-α secreted from DCs is linked to human autoimmune diseases such as IBD and psoriasis." (PMID 33907502, 2021). "Blocking the NF-κB signaling and TNF-α (its canonical pathway inducer) is one of successful approaches of the anti-psoriasis treatment." (PMID 34834106, 2021). "The influence of the TLR2 rs4696480 (T > A) and rs11938228 (C > A, T) polymorphisms has been investigated in 478 patients from Denmark diagnosed with moderate-to-severe psoriasis and treated with anti-TNF medication (n = 376) and UTK (n = 230)." (PMID 33921427, 2021). "Another study by our group confirmed the anti-inflammatory activity of FX due to a reduction in TNF-α levels in LPS-activated THP-1 macrophages and IL-6 and IL-8 production in TNF-α-stimulated HaCaT keratinocytes, an in vitro model of psoriasis." (PMID 34677429, 2021).
psoriasis (continued). "Topical application of SHR168442 in Vaseline exhibited excellent efficacy in the imiquimod-induced and IL-23-induced psoriasis-like skin inflammation mouse models and correlated with the reduction of Th17 pathway cytokines, IL-6, TNFα and IL-17A." (PMID 33911101, 2021). "TNF-α and IL-17, central players in the pathogenesis of psoriasis, are known to impair bone formation." (PMID 34660638, 2021). "TNF-α is a significant inflammatory cytokine that has been well defined to generate a concert of cytokines relevant to the pathogenesis of psoriasis." (PMID 35056961, 2021). "Circulating levels of Th1, Th17, and Th22 cells are increased in psoriasis patients compared to healthy volunteers, and the frequency of Th1 and Th17 cells is decreased after anti-TNF-α therapy." (PMID 34829740, 2021). "As regards psoriatic disease pathogenesis, the pro-inflammatory cytokines sustaining psoriasis development (TNFα, IL17, and IL23) have been found to play a key role in PsA pathogenesis, too." (PMID 34680599, 2021). "Psoriasis patients with severe depressive symptoms were found higher levels of inflammatory cytokines in the peripheral blood such as TNF-α, IL-6, and IL-17 than those with low depressive patients." (PMID 35004741, 2021). "Some current case reports show that patients with psoriasis receiving TNF-α inhibition therapy can recover from the infection, even without any clinical symptoms." (PMID 34938746, 2021). "Human TNF-α has been intensively studied, and drugs (e.g., TNF-α blockers) were developed in the form of TNFα antibodies to treat many diseases, including osteoporosis, psoriasis, arthritis and Crohn disease." (PMID 34869718, 2021). "The interplay between plasmacytoid and myeloid dendritic cells, helper T cells (Th1, Th17, Th22), and mediators such as tumor necrosis factor (TNF)-α, interleukin (IL)-12, IL-23, and IL-17 provides targets for psoriasis drug development." (PMID 34083738, 2021). "These T cells induce psoriasis via the secretion of proinflammatory cytokines such as tumor necrosis factor-α (TNF-α), interleukin (IL)-17A, IL-23, and interferon-γ." (PMID 34445513, 2021). "To date, many treatments for psoriasis have been proposed—such as bone marrow transplantation, drug treatments, or anti-TNF therapy—but all still need to be improved." (PMID 34360845, 2021). "We would encourage researchers to examine the diagnostic and prognostic role of IL1-β, TNF-α, IL-2 and IFN-γ in different psoriasis clinical forms." (PMID 34209865, 2021). "Proinflammatory cytokines such as interleukin-23 (IL-23), IL-17, and tumor necrosis factor α (TNF-α) play critical roles in the initiation and maintenance of psoriasis." (PMID 34722555, 2021). "A study conducted by this research team showed that regular coffee consumption increased IL-6, CRP, and TNF-alpha levels, which translated into clinical severity of psoriasis symptoms." (PMID 35010995, 2021). "TNF-α inhibitors are an efficacious therapy for disease control and improvement of QoL in psoriasis patients with nail psoriasis and concomitant PsA." (PMID 34834435, 2021). "Biologic therapy including anti-TNF-a, IL-17 and IL-12/23 antibodies used in the treatment of psoriasis and PsA appears to be highly effective in the treatment for nail psoriasis as well as small molecule therapies." (PMID 34068890, 2021). "In several autoimmune diseases, increased levels of TNF have been found at inflammation sites, such as in the lesional skin of psoriasis patients." (PMID 33921371, 2021). "Plaque psoriasis’, the most prevalent subtype of psoriasis, pathogenesis primarily involves cytokines TNF-α, IL-17, and IL-23." (PMID 34884596, 2021). "One study analyzed miRNA levels in psoriasis and proposed the use of a new biological therapy (anti-TNF-alpha) to reduce serum miRNA levels (including miR-126) in patients with psoriasis." (PMID 35027969, 2021). "Levels of TNF-alpha has been found to be significantly higher in the skin of psoriasis patients than unaffected people." (PMID 34123557, 2021).